HIF1A (hypoxia inducible factor 1 subunit alpha)
Diseases named in the same sentence as HIF1A in open-access papers (continued):
Sharing a sentence is not in itself a finding about the gene and the disease.
peritonitis (3 papers, 2016 to 2025). Inflammation of the peritoneum (tissue that lines the abdominal wall and covers most of the organs in the abdomen). "Our results indicated that EPOR expression increased in an HIF-1α-dependently manner during acute peritonitis." (PMID 27397585, 2016). "In short, the quantitative expression and distribution of HIF-1α in serum exosomes during peritonitis might be used as an early biomarker to observe the process of bacterial peritonitis." (PMID 34898382, 2022). "We found that IKZF1 inhibition significantly promotes the degradation of HIF-1α without affecting its transcriptional level, further confirming that IKZF1 exacerbates CLP-induced peritonitis by promoting succinate accumulation." (PMID 41019036, 2025).
prediabetes (3 papers, 2019 to 2022). "The fact that the HIF1α and PFKFB3 upregulation and the loss of β-cell function happen concomitantly in prediabetes implicates further the inhibition of β-cell fitness competition at the early β-cell decompensation stage." (PMID 35318430, 2022). "In LOsG-induced prediabetes, although pancreatic ROS stress remained high on LOsG treatment day 38, there were no alterations in mRNA levels of ER stress (XBP1 and BIP), inflammation (IL6 and IL1β), and hypoxia-responsive (HIF1α and GAPDH) genes between LOsG- and sham-treated groups." (PMID 30975975, 2019).
prion disease (3 papers, 2014 to 2021). A transmissible disease that is caused by a protein that is able to induce abnormal folding of normal cellular proteins, leading to characteristic spongiform brain changes, which are associated with neuronal loss without an inflammatory response. "In the future, we will further study the neuroprotective effects of hinokitiol, autophagy and the HIF-1α pathway in mouse models to examine hinokitiol's potential therapeutic role in prion disease." (PMID 27074563, 2016). "However, little is known about the molecular mechanisms through which gingerol mediates the expression of HIF-1α in the pathogenesis of prion diseases." (PMID 25231392, 2014). "In conclusion, our results indicate that gingerol has therapeutic potential for use in the treatment or prevention of prion diseases by exerting inhibitory effects on the catalytic activity of PHD2, thus stabilizing HIF-1α." (PMID 25231392, 2014).
psoriasis vulgaris (3 papers, 2022 to 2024). Plaque psoriasis is the most common presentation of psoriasis. "HIF-1α-induced glycolysis has been associated with keratinocyte proliferation in psoriasis vulgaris." (PMID 36961533, 2023). "Subudhi et al48 showed metabolic coordination between skin epithelium and type 17 immunity in plaque psoriasis, in which blocking HIF1α in psoriatic lesions ex vivo impaired glycolysis and phenocopied IL‐17 inhibition." (PMID 39711043, 2024). "Upregulated expressions of HIF-1α has been detected in psoriasis vulgaris and other autoinflammatory diseases related to Th17-mediated inflammation." (PMID 36961533, 2023). "In the skin and serum of patients with psoriasis vulgaris, increased expression of HIF-1α has been reported, whereas HIF-1α expression in the skin and serum of patients with hidradenitis suppurativa (HS) has not yet been studied." (PMID 36961533, 2023). "Another study found that HIF1A might promote the glycolysis process of psoriasis Vulgaris by increasing the expression of CD147 and GLUT1." (PMID 35265149, 2022).
pterygium (3 papers, 2020 to 2023). A wedge-shaped fibrovascular lesion arising from the bulbar conjunctiva and extending to the cornea. "Immunohistochemical staining was performed with antibodies against HIF1α and HIF2α, respectively, on 55/84 primary pterygium specimens, 6/28 recurrences and 20/20 control tissues (healthy conjunctiva)." (PMID 37684398, 2023). "Analysis of variance (ANOVA) of epithelial HIF1α and HIF2α immunoreactivity performed within each category 2, 3 and 4 in pterygium, recurrences and controls revealed significant differences between HIF1α and HIF2α in primary pterygium." (PMID 37684398, 2023). "The paracrine modality would activate the PI3K/AKT pathway, carrying out the downstream transcription of HIF1A, whose protein is a crucial factor involved in the occurrence and development of pterygium." (PMID 36901760, 2023). "The aim of this study using immunohistochemistry (IHC) was to investigate whether in pterygium besides HIF1α, also HIF2α is expressed." (PMID 37684398, 2023). "HIF1α and HIF2α immunoreactivity was present in primary and recurrent pterygium." (PMID 37684398, 2023). "Until today, only the HIF1α protein has been studied in pterygium." (PMID 37684398, 2023). "Unexpectedly, primary and recurrent pterygium revealed lower immunoreactivity of HIF1α (11% ± 20%, and 18% ± 36%) and HIF2α (38% ± 31%, and 21% ± 27%), respectively, in epithelial cells when compared to healthy conjunctiva (HIF1α: 46% ± 30% and HIF2α: 66% ± 31%)." (PMID 37684398, 2023). "Their unpublished results include a higher expression of HIF-1α and HIF-2α in the controls compared with pterygium specimens." (PMID 32458097, 2020). "In recurrent pterygium and healthy conjunctiva, immunoreactivity levels of HIF2α were higher than those of HIF1α as well; however, differences between both isoforms were not significant." (PMID 37684398, 2023). "Besides HIF1α, no other HIF-isoform, e.g., HIF2α, has been described in pterygium up to now." (PMID 37684398, 2023).
pulmonary sarcoidosis (3 papers, 2019 to 2025). Sarcoidosis affecting the lung parenchyma. "Both VEGFA and HIF1A are associated with susceptibility and progression of COPD with HIF1A, they also play important roles in pulmonary sarcoidosis and acute lung injury." (PMID 30700303, 2019).
pulpitis (3 papers, 2021 to 2024). Inflammation of the dental pulp. "We found the upregulation of HIF-1α accompanied by the activation of the NLRP3 inflammasome during the development from reversible to irreversible pulpitis, which indicated the link between hypoxic conditions and pulpal inflammation." (PMID 39343901, 2024). "More work is required to investigate the correlation between hypoxic microenvironment and pulpitis in vivo, attempting to control the progression of pulpitis and preserve vital pulp by alleviating the hypoxic microenvironment in the pulp cavity or pharmacological interventions targeting HIF-1α." (PMID 39343901, 2024). "This study aimed to investigate the role of HIF-1α in the regulation of NLRP3 inflammasome pathway via NF-κB signaling under hypoxic conditions with or without LPS in human dental pulp fibroblasts (HDPFs) during the progression of pulpitis." (PMID 39343901, 2024). "In summary, our study revealed a positive correlation between the expression levels of P2X7/HIF-1α in microglia of MDH and the degree of dental pain induced by pulpitis." (PMID 36385758, 2022). "HIF-1α served as a positive regulator of NLRP3/ASC/CASP1 inflammasome pathway activation via NF-κB signaling in HDPFs in the sterile pulpal inflammation and caries-related pulpitis microenvironment." (PMID 39343901, 2024). "It has been reported that HIF-1α promotes the expression of IL-1β and TNF-α in inflammatory dental pulp cells, and HIF-1α is involved in the development of dental pulpitis from reversible to irreversible pulpitis." (PMID 36385758, 2022).
respiratory distress syndrome (3 papers, 2015 to 2024). "Alveolar epithelial-specific HIF-1α deficient mice suffer from respiratory distress syndrome with thickened alveolar septum and die within hours." (PMID 38717999, 2024). "We have recently shown that the inducible loss of Hif-1α in lung epithelium starting at E4.5 leads to death within an hour of parturition, with symptoms similar to neonatal respiratory distress syndrome (RDS)." (PMID 26422241, 2015). "We show that mice containing only one functional copy of Hif-1α still have very low viability in the earlier developmental time points and that heterozygosity in these mice does not necessarily rescue the neonatal respiratory distress syndrome phenotype for Hif-1α." (PMID 26422241, 2015).
rhinitis (3 papers, 2018 to 2023). An inflammation of the mucous membrane lining the nose, usually associated with nasal discharge. "Studies have reported increased HIF-1α expression in asthmatic and rhinitis patients and suggested direct involvement of HIF-1α in allergic airway inflammation." (PMID 37316684, 2023).
scleroderma (3 papers, 2013 to 2022). Scleroderma is a rare autoimmune connective tissue disorder characterized by abnormal hardening of the skin and, sometimes, other organs. "In particular, hypoxia up-regulates CTGF expression through activation of HIF-1α in dermal fibroblasts from scleroderma patients, and thereby contributes to the progression of skin fibrosis." (PMID 23663495, 2013). "HIF-1α has been postulated to be dysregulated in various pathologic conditions, which was also detected throughout the keratinocytes of the epidermis in all skin biopsies obtained from scleroderma patients." (PMID 35231032, 2022). "The 2-methoxyestradiol (2-ME), a natural endogenous metabolite of 17b-estradio, reduced HIF-1a, CTGF, and collagen I induced by hypoxia via PI3K/Akt/mTOR/HIF-1a and inhibited the proliferation of fibroblasts, which is expectable to become a promising agent to treat scleroderma." (PMID 34067630, 2021).
testicular cancer (3 papers, 2023 to 2024). A primary or metastatic malignant neoplasm that affects the testis. "Based on the results of detecting 35 apoptosis-related proteins, it can be inferred that IATL is associated with HIF-1α signaling pathways and TNF signaling pathways, triggering downstream signal pathways that affect testicular cancer cell survival." (PMID 39382942, 2024). "Testicular cancer was used as a positive control for hypoxia-inducible factor 1 (HIF-1α), with clear nuclear positivity." (PMID 37446252, 2023).
Theileria infection (3 papers, 2014 to 2023). "In theileriosis, the T. annulata has been shown to induce the HIF1a (a subunit of HIF1) activation." (PMID 31231548, 2019). "As both NF-κB and AP-1 are induced by Theileria infection, it is likely that these two transcription factors participate in the rapid induction of hif-1α transcription post sporozoite invasion." (PMID 24112286, 2014). "Given that Theileria infection of leukocytes transforms them into tumour-like cells we decided to ask whether T. annulata infection also generates a host cell oxidative stress response that activates HIF-1α and what are the consequences of HIF-1α induction on host cell glycolysis." (PMID 24112286, 2014).
uveitis (3 papers, 2012 to 2025). An inflammatory process affecting a part of or the entire uvea. "Low dose rapamycin can potentially impact on ocular vasculature during uveitis by altering HIF-1α and VEGF expression." (PMID 22574188, 2012). "Hypoxia-inducible factor-1α (HIF-1α) and vascular endothelial growth factor (VEGF) are implicated in inflammation and ocular pathology including uveitis." (PMID 22574188, 2012). "Previously research reported that downstream HIF-1α signaling could facilitate Th17 differentiation; so we investigated whether melatonin alleviated uveitis via the oxidative stress/TXNIP/HIF-1α signaling axis." (PMID 35624485, 2022). "Hypoxia-inducible factor 1 alpha (Hif1α) is confirmed as an up-regulated EAU-associated differentially expressed gene (DEG) in Th1, Th17, and Treg cells, and enhanced Hif1α expression in CD4+ T cells was conserved and may promote their proliferation in uveitis patients." (PMID 40867565, 2025).
vitiligo (3 papers, 2019 to 2023). Generalized well circumscribed patches of leukoderma that are generally distributed over symmetric body locations and is due to autoimmune destruction of melanocytes. "And the expression of hypoxia-inducible factor (HIF-1α) also increases in CD8+ T cells from patients with vitiligo." (PMID 35222802, 2022). "The pathogenesis of vitiligo is closely related to oxidative stress, and our data suggest that overexpression of hypoxia-inducible factor-1α (HIF-1α) increases the expression of occludin." (PMID 35222802, 2022). "To further investigate the mechanisms of the overexpression of HIF-1α in vitiligo CD8+ T cells, we confirmed the DNA methylation status of the HIF-1α promoter in vitiligo patients." (PMID 31885781, 2019). "In this study, we have demonstrated that the mRNA and protein expression levels of HIF-1α are elevated in vitiligo." (PMID 31885781, 2019). "In our study, the expression levels of PIK3CB and HIF-1α were both increased in the patients with vitiligo." (PMID 31885781, 2019). "We also validated the DNA methylation levels of the HIF-1α and F2RL1 promoter to explore the potential pathogenic mechanisms regarding CD8+ T cells in vitiligo." (PMID 31885781, 2019). "The results showed that two specific CpG sites of the HIF-1α promoter were hypomethylated in patients with vitiligo." (PMID 31885781, 2019). "Thus, oxidative stress in vitiligo drives increased HIF-1α expression in CD8+ T cells, and HIF-1α overexpression and enhancement upregulate occludin expression, which mediates the adhesion of CD8+ T cells to melanocytes." (PMID 35222802, 2022). "Thus, we suggest that the higher levels of HIF-1α are related to its DNA hypomethylation in vitiligo." (PMID 31885781, 2019). "In addition, we uncovered a potential role for DNA hypomethylation of HIF-1α in CD8+ T cells of vitiligo." (PMID 31885781, 2019). "However, studies regarding the exact mechanisms about the interplay between PIK3CB and HIF-1α in vitiligo still need to be extended." (PMID 31885781, 2019). "Based on this, we speculated that elevated HIF-1α may be caused by environmental factor-induced ROS via DNA hypomethylation mechanism, which may further promote the activation of CD8+ T cells in vitiligo." (PMID 31885781, 2019). "The HIF-1α gene was identified as being upregulated in vitiligo for the first time in this study." (PMID 31885781, 2019). "Two CpG sites of the HIF-1α promoter were hypomethylated in vitiligo CD8+ T cells." (PMID 31885781, 2019). "Thus, occludin was upregulated in vitiligo via the HIF-1α signaling pathway." (PMID 35222802, 2022). "Interestingly, our preliminary study found that HIF-1α was high ranked in vitiligo CD8+ T cells." (PMID 35222802, 2022). "In conclusion, HIF-1α, F2RL1, and PIK3CB may act as novel drivers for vitiligo, which are all closely associated with reactive oxygen species and possibly contribute to the activation and/or migration of melanocyte-specific CD8+ T cells in vitiligo." (PMID 31885781, 2019). "Oxidative stress in vitiligo drives increased HIF-1α expression, and HIF-1α overexpression and enhancement upregulate occludin expression, which mediates the adhesion of CD8+ T cells to melanocytes." (PMID 35222802, 2022). "The mRNA and protein expression levels of PIK3CB, HIF-1α, and F2RL1 were all elevated in CD8+ T cells from peripheral blood in vitiligo." (PMID 31885781, 2019). "Ultimately, we found that the mRNA and protein levels of HIF-1α, F2RL1, and PIK3CB genes were all elevated in the CD8+ T cells in vitiligo." (PMID 31885781, 2019). "Interestingly, our group previously found increased HIF-1α expression in the peripheral CD8+ T cells and vitiligo skin lesions." (PMID 35222802, 2022). "HIF-1α was also highly expressed in fibroblasts under the hypoxic environment, which may explain the increased OCLN expression in the fibroblasts from vitiligo patients." (PMID 35222802, 2022). "HIF-1α and PIK3CB were significantly increased in lesional skin of vitiligo." (PMID 31885781, 2019).
vitiligo (continued). "Notably, we found that HIF-1α (p < 0.0001) and PIK3CB (p < 0.0001) were significantly increased in vitiligo." (PMID 31885781, 2019). "Intriguingly, we found that the CpG sites of HIF-1α-8-40 in 5-azaC-treated-normal CD8+ T cells were hypomethylated compared to untreated-normal CD8+ T cells (0.68% (0.51%-0.83%) vs. 0.87% (0.75%-1.08%), p < 0.01), which is consistent with the results of vitiligo CD8+ T cells." (PMID 31885781, 2019).
xeroderma pigmentosum group C (3 papers, 2021 to 2022). An autosomal recessive inherited disorder caused by mutations in the XPC gene. "A recent study was conducted to show the effect of Oroxylin A in hypoxia-induced cisplatin resistance by inhibiting HIF-1α-mediated xeroderma pigmentosum group C (XPC) transcription." (PMID 35163459, 2022). "Interestingly, another study revealed that oroxylin A directly interacts with HIF-1α and inhibits the DNA binding property of HIF-1α, decreasing the transcription of xeroderma pigmentosum group C (XPC), a DNA repair gene." (PMID 34575983, 2021).
Acidosis (2 papers, 2020 to 2021). Abnormal acid accumulation or depletion of base. "Acidosis has also been reported to enhance radioresistance by modulating the intracellular levels of HIF-1α." (PMID 34249682, 2021). "Lactic acidosis diminished GLUT1/GLUT4 expression and glucose consumption in A-549, but not in A-427 cells, and induced differential expression of HIF-1α, AMPK, and CS transcripts." (PMID 32596143, 2020).
acne inversa (2 papers, 2023). "The objective of the study is to demonstrate is there a role for HIF-1α in the pathogenesis of hidradenitis suppurativa, and its relation to HS severity." (PMID 36961533, 2023). "Notably, we recently detected increased levels of expression of HIF-1α in the lesional skin of patients with acne inversa (hidradenitis suppurativa)." (PMID 37998335, 2023).
acute monocytic leukemia (2 papers, 2016 to 2021). Acute monoblastic leukemia (AML-M5), is one of the most common subtypes of acute myeloid leukemia (AML) that is either comprised of more than 80% of monoblasts (AML-M5a) or 30-80% monoblasts with (pro)monocytic differentiation (AML-M5b). "Taken together, these data indicate that HIF-1α activates a pro-invasive gene signature in acute monocytic leukemia that leads to increased motility, invasion and transendothelial migration, and inhibition of HIF-1α impairs important functions of monocytic leukemia blasts." (PMID 27447550, 2016). "By applying a list of validated HIF-1α-target genes to different AML sub-types, we identified a HIF-1α signature that typifies acute monocytic leukemia when compared with all other AML sub-types." (PMID 27447550, 2016). "Moreover, in human acute monocytic leukemia (THP-1) cells, VSV infection, HSV-1 infection, or LPS treatment activated HIF-1α expression." (PMID 34408131, 2021). "In conclusion, our studies demonstrate that HIF-1α exerts oncogenic functions in AML-M5 and prompt future examination on the role of compounds that inhibit HIF factors in combination with other therapies for the treatment of acute monocytic leukemia." (PMID 27447550, 2016).
age (2 papers, 2024). A temporal measurement of the time period elapsed since an identifiable point in the life cycle of an organism. "Because HIF-1α has been given an essential role in wound healing, investigating the HIF-1α signaling pathway may open novel enquiries for future studies in age-related corneal epithelium diseases." (PMID 38739085, 2024).
age-related hearing loss (2 papers, 2016 to 2022). "Our results showed that Mn-mediated age-related hearing loss involved an increased level of Hif-1α protein with less hydroxylation at proline 564 and decreased expression and phosphorylation levels of c-Ret in SGNs." (PMID 27824154, 2016). "A previous study showed that age-related hearing loss is associated to HIF-1α protein in SGNs27." (PMID 27824154, 2016).
airway hyperresponsiveness (2 papers, 2020 to 2026). "For instance, myeloid-specific deletion of HIF-1α in mice results in reduced airway hyperresponsiveness (AHR), and HIF-1α deficient eosinophils show reduced chemotaxis." (PMID 33519814, 2020).
alcoholic hepatitis (2 papers, 2016 to 2018). Acute hepatitis resulting from ingestion of alcohol. "Studies indicate that alcoholic hepatitis accelerates early hepatobiliary cancer by increasing stemness and miR122-mediated HIF-1α activation." (PMID 29449541, 2018).